DOT1L (DOT1 like histone lysine methyltransferase)
Diseases named in the same sentence as DOT1L in open-access papers (continued):
Sharing a sentence is not in itself a finding about the gene and the disease.
breast carcinoma (continued). "We found that DOT1L expression levels were generally elevated across breast cancer subtypes, although the difference between HER2-positive tumors and normal tissues was not statistically significant." (PMID 41299712, 2025). "CRISPR/Cas9-mediated knockout of STING in breast cancer cells significantly suppressed the IFN signaling activated by DOT1L inhibition and attenuated the anti-tumor effect." (PMID 41299712, 2025). "In another study, EPZ004777-mediated DOT1L inhibition was found to be effective in increasing E-cadherin levels in breast cancer cells by suppressing key transcription factors involved in the epithelial–mesenchymal transition (EMT)." (PMID 40136427, 2025). "Further study to clarify the clinical usefulness of DOT1L inhibition in breast cancer is therefore warranted." (PMID 41299712, 2025). "In the present study, we aimed to clarify the anti-tumor effect of DOT1L inhibition in breast cancer." (PMID 41299712, 2025). "Transcriptome and epigenome analysis revealed that DOT1L inhibition activated transcription of a number of interferon (IFN)-related genes (IRGs) in breast cancer cells." (PMID 41299712, 2025). "We detected significantly lower levels of histone H3 K79 mono- (H3K79me1), di- (H3K79me2) and trimethylation (H3K79me3) in breast cancer cells treated with a DOT1L inhibitor." (PMID 41299712, 2025). "In the present study, we identified a novel mechanism by which DOT1L inhibition exerts its anti-tumor effect in breast cancer." (PMID 41299712, 2025). "We also demonstrate that DOT1L inhibition suppresses proliferation of HER2-positive breast cancer cells, at least in part, by suppressing ERBB2 expression." (PMID 41299712, 2025). "In the present study, we identified a novel mechanism by which DOT1L inhibition exerts its anti-breast cancer effects." (PMID 41299712, 2025). "When the expression degree for DOT1L is too high in breast cancer, the transcriptional activity of BCAT is significantly enhanced, which also affects the growth performance for breast tumor cells along with enhances their invasiveness." (PMID 38495505, 2024). "DOT1L inhibition also prevented the breast cancer progression through suppressing the EMT of breast epithelia cells." (PMID 38172378, 2024). "Recently, it has been proved that DOT1L has a crucial role in the initiation and progression of various tumor types, such as lung cancer, breast cancer, ovarian cancer, renal clear cell carcinoma, and neuroblastoma." (PMID 39307938, 2024). "The resulting epigenetic activation of EMT transcription factors promotes EMT-induced cancer stem cell properties and enhances the invasive and metastatic abilities in breast cancer, possibly reversed by the use of DOT1L inhibitor." (PMID 37369946, 2023). "One of the only known histone 3 lysine 79 (H3K79) methyltransferases, is the histone methylase disruptor silencing 1 like (DOT1L) which has critical role in the development of breast cancer and is a potential therapeutic target for invasive breast cancer." (PMID 36185256, 2022). "Recently, growing attention has been paid to DOT1L role in breast cancer and its possible targeting as a novel therapeutic approach." (PMID 35495127, 2022). "We also found DOT1L overexpression in in other solid cancer types including breast cancer, glioblastomas relative to normal tissues." (PMID 32814769, 2020). "EPZ004777, the first reported DOT1L inhibitor, inhibits self-renewal and metastatic potential of breast cancer." (PMID 33343366, 2020). "In breast cancers, DOT1L forms a transcriptionally active complex with c-Myc and p300 to facilitate H3K79 methylation and acetylation in the promoter regions of EMT-TFs and enhance their de-repression, consequently promoting EMT-induced CSC properties." (PMID 33343366, 2020).
breast carcinoma (continued). "As previously shown in breast cancer, DOT1L inhibition resulted in a dose-dependent inhibition of ESR1 gene expression in both cell lines, as demonstrated by a decrease of both ERα mRNA and protein levels upon EPZ treatment." (PMID 31689915, 2019). "Still, several researches have shown that Dot1l takes part in the progression of many other tumors, such as lung cancer, colorectal cancer and breast cancer." (PMID 27713173, 2016). "A bioinformatics search found the expression levels of DOT1L correlate with breast cancer as well as a panel of genes that promote proliferation of the malignancy." (PMID 27316347, 2016). "By using immunohistochemical analysis of DOT1L, weinvestigated the relationship of DOT1L with clinicopathological features in 182human breast cancers." (PMID 26199140, 2015). "On the basis of our results, wesuggest that DOT1L is a critical indicator of breast cancer aggressiveness thatinduces breast cancer initiation and progression, invasion and metastasis because ofits enhancement function of the CSC and EMT." (PMID 26199140, 2015). "Analysis also showed DOT1L expression levels are significantly correlated with estrogen receptor negative (ER−) breast cancers, although a smaller proportion of ER+ breast cancers still express relatively high levels of DOT1L." (PMID 25359765, 2014). "Similar to DOT1L-specific inhibitors 1 and 2, compound 4 also exhibited strong anti-proliferation activity against DOT1L+ breast cancer cells, mainly because of H3K79 methylation inhibition." (PMID 25359765, 2014). "We tested the activity of DOT1L specific inhibitors 1 and 2 against a panel of five breast cancer cell lines." (PMID 25359765, 2014). "For a 15-day treatment, these two inhibitors had strong activity against proliferation of MDA-MB231, BT549 (both showing ER−) and MCF-7 (ER+) breast cancer cells expressing relatively high levels of DOT1L, with EC50 values of 0.19 – 1.4 μM." (PMID 25359765, 2014). "DOT1L/H3K79 methylation inhibition selectively inhibited proliferation, induced differentiation, and reduced cell migration and invasiveness of breast cancer cells with a relatively high DOT1L." (PMID 25359765, 2014). "DOT1L inhibition selectively inhibited proliferation, self-renewal, metastatic potential of breast cancer cells and induced cell differentiation." (PMID 25359765, 2014). "Notably, DOT1L inhibition induced DNA damage and upregulated levels of cytoplasmic DNA in breast cancer cells." (PMID 41299712, 2025). "Taken together with these observations, our results demonstrate that the anti-breast cancer effects of DOT1L inhibition are mediated via modulation of a variety of biological processes, including growth and apoptosis signaling, EMT, CSC activity, and innate immune signaling." (PMID 41299712, 2025). "To further clarify the anti-tumor mechanism of DOT1L inhibition in HER2-positive breast cancer cells, we performed Single-cell Assay for Transposase-Accessible Chromatin sequencing (scATAC-seq) analysis in SKBR3 cells treated with DMSO, SGC0946 or EPZ-5676 for 6 to 12 days." (PMID 41299712, 2025). "Likewise, we found increased levels of γH2AX, a marker of DNA damage, in the cytoplasmic and nuclear fractions of breast cancer cells treated with a DOT1L inhibitor." (PMID 41299712, 2025). "To assess whether DOT1L inhibition activates immune responses against breast cancer cells, we co-cultured PBMCs, including lymphocytes, with breast cancer cells pre-treated with a DOT1L inhibitor." (PMID 41299712, 2025). "We also found that DOT1L inhibition downregulates ERBB2 expression in HER2-positive breast cancer cells, which may contribute to the anti-tumor effect." (PMID 41299712, 2025). "Moreover, DOT1L inhibition increased the levels of phosphorylated STING in breast cancer cells, indicating activation of the cytosolic DNA sensor pathway." (PMID 41299712, 2025).
breast carcinoma (continued). "Moreover, scATAC-seq analysis revealed that DOT1L inhibition suppressed expression of ERBB2 in HER2-positive breast cancer cells." (PMID 41299712, 2025). "Recent studies suggest DOT1L is an exploitable therapeutic target in breast cancer." (PMID 41299712, 2025). "We next analyzed the effect of DOT1L inhibition on chromatin status in breast cancer cells." (PMID 41299712, 2025). "In addition, fluorescence staining of double-stranded DNA (dsDNA) revealed cytoplasmic DNA foci in breast cancer cells treated with a DOT1L inhibitor, indicating increased levels of cytosolic DNA upon DOT1L inhibition." (PMID 41299712, 2025). "Downregulation of DOT1L induces a G1 arrest and cellular senescence in lung cancer cells and inhibition of DOT1L suppresses the proliferation, self‐renewal, and metastasis of breast cancer cells." (PMID 39307938, 2024). "It had been reported that DOT1L could maintain leukemic gene expression, promote the phenotype differentiation of neuronal, myocardial cells and breast cancer cells." (PMID 38172378, 2024). "Moreover, DOT1L enhanced activity in human breast cancer leads to dissociation of HDAC1 and DNMT1 proteins from promoters, which inhibits HDAC activity and DNA methylation." (PMID 37369946, 2023). "When combined, these results show for the first time a functional interdependence between Dot1L and menin in estrogen-sensitive and AE-resistant breast cancer, and point to BAZ1B as a member of a Dot1L-menin regulatory network exploitable for devising new ways to treat endocrine-resistant BC." (PMID 35850772, 2022). "Thus, it has been shown that the expression of BCAT1, which is regulated by the DOT1L histone methyltransferase, promoted the migrations of breast cancer cells." (PMID 32571264, 2020). "In addition, the MDA-MB-231 and HCC1937 cells exhibited the relatively higher DOT1L expression levels and downregulated E-cadherin level among the tested human breast cancer cell lines." (PMID 32244385, 2020). "The histone methyltransferase Disruptor of telomeric silencing-1-like (DOT1L), which is a modulator of ERα transcriptional activity in breast cancer, controls chromatin functions involved in tumor initiation and progression and has been proposed as a prognostic OC biomarker." (PMID 31689915, 2019). "Moreover, DOT1L inhibitors have shown effective suppression of proliferation, migration, and invasion of breast cancer." (PMID 28114995, 2017). "However, functional mechanism of the oncogenic potential andclinical relevance of DOT1L in solid tumours including breast cancer remain stillunclear." (PMID 26199140, 2015). "Here, we report that DOT1L is a novel drug target for breast cancer." (PMID 25359765, 2014). "Given ~50% breast cancers in the clinic express relatively high levels of DOT1L, this finding could have a high impact to breast cancer research and treatment." (PMID 25359765, 2014). "Given that H3K79 methylation is a master regulator for gene transcription, a whole-genome profiling was performed to determine how DOT1L inhibition changes gene expression, in order to find the mechanism by which these compounds reduce proliferation of breast cancer cells." (PMID 25359765, 2014). "Moreover, higher DOT1L levels in ~50% breast cancers correlate with overexpression of ~20 pro-proliferation genes in the left-panel of the PAM50 gene set (p < 0.001)." (PMID 25359765, 2014). "Overall, we showed that DOT1L is a potential drug target for breast cancer." (PMID 25359765, 2014). "In addition, our observation that DOT1L inhibition upregulates HLA class I expression in breast cancer cells suggests it may sensitize cancer cells to tumor immunotherapy." (PMID 41299712, 2025). "In addition, a recent study revealed that DOT1L is a novel cofactor of estrogen receptor α (ERα), acting to regulate estrogen target genes, and that DOT1L inhibition suppresses proliferation of antiestrogen-resistant breast cancer cells." (PMID 41299712, 2025).
breast carcinoma (continued). "Although the DOT1L did not affect the survival of ER-positive breastcancer patients who have a favourable outcome following anti-oestrogen therapy, ourclinical data support the notion that DOT1L could be a therapeutic target in moreaggressive ER-negative and metastatic human breast cancers." (PMID 26199140, 2015). "Therefore, our findings demonstrate functional role of potential oncogeneDOT1L in promoting multistep breast carcinogenesis associated with EMT and stemcell-like phenotype as a novel epigenetic regulator of EMT-TFs, suggesting DOT1L to be apromising target for aggressive breast cancer therapy." (PMID 26199140, 2015). "Therefore, DOT1L could be animportant oncogene and a novel target in aggressive breast cancer therapy." (PMID 26199140, 2015). "In conclusion, our findings show that DOT1L inhibition induces DNA damage and activates STING-mediated IFN signaling in breast cancer cells." (PMID 41299712, 2025). "Taken together with these reports, our findings suggest that DOT1L inhibition disrupts DNA damage responses, which leads to upregulation of cytosolic DNA and activation of the STING pathway in breast cancer cells." (PMID 41299712, 2025). "To confirm the anti-tumor effects of DOT1L inhibitors (SGC0946, EPZ-5676) in breast cancer, we used the MCF7 (ER-positive, HER2-negative) and SKBR3 (ER-negative, HER2-positive) cell lines for the analysis." (PMID 41299712, 2025). "Menin also complexes with the H3K79 histone methyltransferase DOT1L and the epigenetic reader protein BAZ1B in ER-positive luminal breast cancer cells." (PMID 39336822, 2024). "CSCs aggregate to form microspheres 9, 10, and the DOT1L gene can combine with the c-Myc gene; in this process, mRNA expression of EMT genes is increased, which controls how invasively breast cancer cells can spread." (PMID 38495505, 2024). "About the H3K79 methyltransferase DOT1L, an example that clearly illustrates the crosstalk between several epigenetic players to activate EMT regulators has been described in breast cancer." (PMID 37369946, 2023). "MYC increases breast cancer stem cell-like properties and EMT by binding to DOT1L and p300, which stimulates SNAIL, ZEB1, ZEB2 transcription and promotes lysine-79 methylation and H3 acetylation through gene epigenetic modification." (PMID 33390842, 2021). "BCAT1 is one DOT1L target gene regulated by H3K79 methylation and is responsible for DOT1L-mediated cell migration in breast cancer cells." (PMID 32042335, 2020). "On the other hand, overall survival is significantly impaired in ERα-positive patients who show high DOT1L expression, which suggests that a combined activity of both these factors might lead to a more aggressive behavior of OC cells, by possibly acting on common targets in breast cancer." (PMID 31689915, 2019). "Protein and mRNA expression assays confirmed co-expression of both ERα and DOT1L in PEO cells, even though their level was slightly different between the two, and lower when compared to those of breast cancer MCF7 cells used for comparison." (PMID 31689915, 2019). "Because the DOT1L enzymatic activity of H3K79me wasalso important for CSC, EMT and metastasis in our study, these DOT1L-target drugsmight also be useful for breast cancer therapy." (PMID 26199140, 2015). "In conclusion, we suggest DOT1L to be critical for regulation of EMT-induced tumourinitiation and progression in breast cancer as an important epigenetic modifier ofEMT-TFs by collaborating with the c-Myc-p300 complex." (PMID 26199140, 2015). "First, although our results suggest that DOT1L inhibition activates innate immune responses in breast cancer cells, we did not assess the effect of DOT1L inhibition on tumor immune responses using an in vivo model." (PMID 41299712, 2025). "The DOT1L inhibitor EPZ004777 downregulated ERα levels and markedly decreased tumor size after 3 weeks of treatment in hormone-positive and anti-estrogen-resistant breast cancer cells." (PMID 35453496, 2022).
breast carcinoma (continued). "MiR-133b played tumor suppressing roles in several malignancies through regulating in gastric cancer, targeting Sox9 in breast cancer, negatively regulating EMP2 in glioma, targeting methyltransferase DOT1L in colorectal cancer, and targeting EGFR in esophageal squamous cell carcinoma." (PMID 33816233, 2021). "DOT1L interacts with c-MYC and p-300 for activating EMT in breast cancer." (PMID 32257110, 2020). "Besides, DOT1L act as an oncogene by activating BAT1 and estrogen receptor α (ERα) to promotes migration and sphere formation of breast cancer." (PMID 31888761, 2019). "In this study, we find that DOT1L forms a novel transcriptional active complex with c-Mycand p300 to enhance epigenetic derepression of EMT-TFs and consequently promoteEMT-induced CSC properties in human breast cancer." (PMID 26199140, 2015). "In this study, we demonstrated that cooperation of DOT1L with c-Myc-p300 is importantfor regulation of both the EMT and CSC in breast cancer by epigenetic activation ofEMT-TFs, providing a novel mechanism of epigenetic regulation of DOT1L-mediatedtranscription of EMT enhancers." (PMID 26199140, 2015). "Overall, these observations showed that H3K79 methylation is important for DOT1L+ breast cancer (regardless of ER status) and DOT1L inhibition selectively inhibits proliferation of these cells." (PMID 25359765, 2014). "Our results support the hypothesis that DOT1L inhibition suppresses breast cancer cell proliferation by activating STING and types I and III IFN signaling, but further study will be necessary to clarify the effect of DOT1L inhibition in TNBC cells with chromosomal instability." (PMID 41299712, 2025). "Thus, in breast cancer, epigenetic regulation mediated by 2HG and DOT1L may upregulate hBCATc in TNBC, which has been demonstrated to mediate proliferation and migration in breast cancer." (PMID 33367952, 2021). "Besides, DOT1L can also form a complex with c-Myc and p300 to control the expression of EMT-related transcriptional factors and promote EMT-induced cancer stem cell properties in human breast cancer." (PMID 31888761, 2019). "DOT1L also forms a novel transcriptional active complex with c-Myc and p300 to enhance epigenetic depression of epithelial-mesenchymal transition-related transcriptional factors (EMT-TFs) and promote EMT-induced cancer stem cell (CSC) properties in human breast cancer." (PMID 31888761, 2019). "Mechanistically, inhibition of DOT1L/H3K79 methylation can impair self-renewal and metastatic potential, induce differentiation and down-regulate many pro-proliferation genes, all of which contribute to significantly reduced proliferation of these breast cancer cells." (PMID 27316347, 2016). "DOT1L-specific inhibitors 1 and 2 were found to have strong activity against proliferation of DOT1L+ breast cancer cells with EC50 values as low as 190 nM, but these compounds were inactive against DOT1L−/low breast or non-breast cancer cells." (PMID 25359765, 2014). "Knockdown of DOT1L and pharmacological inhibition (by e.g., compound 1) showed inhibition of H3K79 methylation and cell proliferation of several DOT1L+ breast cancer cell lines with EC50 of 0.19–1.4 μM, while DOT1Llow breast cancer cells were not sensitive to DOT1L inhibition." (PMID 27316347, 2016). "In addition, DOT1L is not significantly correlated with expression of human epithelial growth factor receptor 2 (HER2), a biomarker for another clinically important subtype of breast cancer." (PMID 25359765, 2014). "Notably, in the absence of DOT1L inhibition, STING knockout cells exhibited higher levels of apoptosis than control cells, suggesting that basal levels of STING expression may inhibit apoptosis in breast cancer cells." (PMID 41299712, 2025).